PALM3 (paralemmin 3)
Description:
ATP-binding protein, which may act as a adapter in the Toll-like receptor (TLR) signaling.
Tractability: Antibody: UniProt places it where antibodies can reach, with medium confidence; its Gene Ontology location is reachable by antibodies, with medium confidence; the Human Protein Atlas places it where antibodies can reach. PROTAC: its protein half-life has been measured.
Gene: Protein-coding gene on chromosome 19 (14,053,363 to 14,062,076, reverse strand). Ensembl gene ENSG00000187867.
Subcellular location: Cytoplasm; Cell membrane
Subcellular location (Human Protein Atlas): Nuclear bodies; Nucleoplasm; Plasma membrane
Genetic constraint (gnomAD): Loss-of-function variants: 25 observed, 27.39 expected, observed/expected ratio (o/e) 0.91, 90% interval 0.66 to 1.27. The upper end of that interval is the gene's LOEUF score, 1.27, which puts it in group 5 of 6, group 1 being the genes least tolerant of losing a copy. Missense variants: 814 observed, 848.73 expected, observed/expected ratio (o/e) 0.96, 90% interval 0.9 to 1.02. Synonymous variants: 328 observed, 336.9 expected, observed/expected ratio (o/e) 0.97, 90% interval 0.89 to 1.07.
Homologues: Orthologues: macaque PALM3 (94% identical), chimpanzee PALM3 (93% identical), dog PALM3 (68% identical), pig PALM3 (67% identical), mouse Palm3 (55% identical), rat Palm3 (55% identical), zebrafish palm3 (18% identical). Paralogues in human: PALM2AKAP2 (17% identical), PALMD (13% identical), PALM (12% identical).
Diseases named in the same sentence as PALM3 in open-access papers:
PALM3 is named in the same sentence as 5 diseases in open-access papers, as found by Europe PMC text mining. Sharing a sentence is not in itself a finding about the gene and the disease. The quoted sentences say what the papers report.
lung adenocarcinoma (1 paper, 2023). A carcinoma that arises from the lung and is characterized by the presence of malignant glandular epithelial cells. "Meanwhile, downregulation of PALM3 after lipopolysaccharide-stimulation can improve the severity of lung injury and can inhibit pro-inflammatory cytokines in human lung adenocarcinoma cells." (PMID 37731134, 2023).
PALM3 also shares sentences with these, for which no sentence is quoted: tumor (2 papers); Alzheimer disease (1); cardiomyopathies (1); cardiovascular diseases (1).